HMGB4 (high mobility group box 4)
Synonyms: FLJ40388; dJ1007G16.5
Tractability: PROTAC: ubiquitination databases record sites on it.
Gene: Protein-coding gene on chromosome 1 (33,860,475 to 33,864,791, forward strand). Ensembl gene ENSG00000176256.
Subcellular location: Nucleus; Chromosome
Gene Ontology:
Molecular function: protein binding
Biological process: chromatin remodeling
Cellular component: nucleus; chromosome
Genetic constraint (gnomAD): Loss-of-function variants: 1 observed, 0.44 expected, observed/expected ratio (o/e) 2.29. That is too few expected variants to judge how well the gene tolerates losing a copy. Missense variants: 193 observed, 192.66 expected, observed/expected ratio (o/e) 1, 90% interval 0.89 to 1.13. Synonymous variants: 64 observed, 74.75 expected, observed/expected ratio (o/e) 0.86, 90% interval 0.7 to 1.05.
Homologues: Orthologues: macaque HMGB4 (94% identical), rabbit HMGB4 (82% identical), guinea pig HMGB4 (79% identical), pig HMGB4 (78% identical), dog HMGB4 (72% identical), mouse Hmgb4 (72% identical), rat Hmgb4 (67% identical), rat Hmgb4l2 (55% identical), rat Hmgb4l6 (55% identical), rat LOC103694587 (55% identical), rat LOC120099313 (55% identical), zebrafish ubtfl (23% identical), and 3 more. Paralogues in human: HMGB2 (42% identical), HMGB1 (41% identical), HMGB1P1 (38% identical), HMGB3 (38% identical), TOX3 (23% identical), TOX (20% identical), TOX2 (20% identical), UBTF (20% identical), TOX4 (18% identical), TFAM (18% identical), SSRP1 (16% identical), SMARCE1 (15% identical), and 8 more.
Diseases named in the same sentence as HMGB4 in open-access papers:
HMGB4 is named in the same sentence as 11 diseases in open-access papers, as found by Europe PMC text mining. Sharing a sentence is not in itself a finding about the gene and the disease. The quoted sentences say what the papers report.
liver cancer (1 paper, 2020). An epithelial or non-epithelial malignant neoplasm that arises from the liver. "HMGB4 gene expression was down-regulated through the development of liver cancer." (PMID 32986357, 2020).
male infertility (1 paper, 2025). The inability of the male to effect fertilization of an ovum after a specified period of unprotected intercourse. "During adulthood, HMGB4 is localized in neural cells and the testis; additionally, expression of HMGB4 has recently been implicated in male infertility." (PMID 40646788, 2025).
nasopharyngeal carcinoma (1 paper, 2020). A carcinoma arising from the nasopharyngeal epithelium. "Consistent with this study that the HMGB4 gene expression has been down-regulated in nasopharyngeal cancer patients in Indonesia." (PMID 32986357, 2020).
HMGB4 also shares sentences with these, for which no sentence is quoted: cancer (2 papers); colorectal cancer (1); glioblastoma (1); lentivirus infection (1); neurological disorders (1); osteosarcoma (1); Stroke (1); tumor (1).